ECT2 (epithelial cell transforming 2)
Description:
Guanine nucleotide exchange factor (GEF) that catalyzes the exchange of GDP for GTP. Promotes guanine nucleotide exchange on the Rho family members of small GTPases, like RHOA, RHOC, RAC1 and CDC42. Required for signal transduction pathways involved in the regulation of cytokinesis. Component of the centralspindlin complex that serves as a microtubule-dependent and Rho-mediated signaling required for the myosin contractile ring formation during the cell cycle cytokinesis. Regulates the translocation of RHOA from the central spindle to the equatorial region. Plays a role in the control of mitotic spindle assembly; regulates the activation of CDC42 in metaphase for the process of spindle fibers attachment to kinetochores before chromosome congression. Involved in the regulation of epithelial cell polarity; participates in the formation of epithelial tight junctions in a polarity complex PARD3-PARD6-protein kinase PRKCQ-dependent manner. Plays a role in the regulation of neurite outgrowth. Inhibits phenobarbital (PB)-induced NR1I3 nuclear translocation. Stimulates the activity of RAC1 through its association with the oncogenic PARD6A-PRKCI complex in cancer cells, thereby acting to coordinately drive tumor cell proliferation and invasion. Also stimulates genotoxic stress-induced RHOB activity in breast cancer cells leading to their cell death.
Synonyms: ARHGEF31
Tractability: PROTAC: UniProt records ubiquitination sites on it; ubiquitination databases record sites on it.
Gene: Protein-coding gene on chromosome 3 (172,750,682 to 172,821,474, forward strand). Ensembl gene ENSG00000114346.
Subcellular location: Nucleus; Cytoplasm; Cytoplasm, cytoskeleton, spindle; Cleavage furrow; Midbody; Cell junction; Cell junction, tight junction; Cytoplasm, cytoskeleton, microtubule organizing center, centrosome
Subcellular location (Human Protein Atlas): Nucleoplasm; Cytosol
Pathways (Reactome):
Signal Transduction: CDC42 GTPase cycle; G alpha (12/13) signalling events; NRAGE signals death through JNK; RAC1 GTPase cycle; RHOA GTPase cycle; RHOB GTPase cycle
Gene Ontology:
Molecular function: GTPase activator activity; guanyl-nucleotide exchange factor activity; protein binding; protein homodimerization activity; small GTPase binding
Biological process: activation of GTPase activity; activation of protein kinase activity; bicellular tight junction assembly; cellular response to calcium ion; cellular response to hydrogen peroxide; cellular response to ionizing radiation; mitotic cytokinesis; positive regulation of apoptotic process; positive regulation of canonical NF-kappaB signal transduction; positive regulation of cytokinesis; positive regulation of GTPase activity; positive regulation of mitotic cytokinetic process; protein homooligomerization; regulation of attachment of spindle microtubules to kinetochore; regulation of protein kinase activity; nervous system development; positive regulation of neuron differentiation; positive regulation of protein import into nucleus; regulation of small GTPase mediated signal transduction; intracellular signal transduction; regulation of cytokinesis, actomyosin contractile ring assembly
Cellular component: anchoring junction; bicellular tight junction; cell-cell junction; centralspindlin complex; cleavage furrow; cytoplasm; cytosol; midbody; mitotic spindle; nucleoplasm; nucleus; cell cortex; centrosome; spindle
Genetic constraint (gnomAD): Loss-of-function variants: 35 observed, 69.85 expected, observed/expected ratio (o/e) 0.5, 90% interval 0.38 to 0.66. The upper end of that interval is the gene's LOEUF score, 0.66, which puts it in group 2 of 6, group 1 being the genes least tolerant of losing a copy. Missense variants: 583 observed, 723.18 expected, observed/expected ratio (o/e) 0.81, 90% interval 0.75 to 0.86. Synonymous variants: 232 observed, 237.42 expected, observed/expected ratio (o/e) 0.98, 90% interval 0.88 to 1.09.
Homologues: Orthologues: chimpanzee ECT2 (98% identical), macaque ECT2 (96% identical), guinea pig ECT2 (93% identical), rabbit ECT2 (93% identical), dog ECT2 (92% identical), pig ECT2 (92% identical), mouse Ect2 (91% identical), rat Ect2 (90% identical), tropical clawed frog ect2 (76% identical), zebrafish ect2 (69% identical), Drosophila melanogaster pbl (34% identical), Caenorhabditis elegans ect-2 (24% identical).
Diseases named in the same sentence as ECT2 in open-access papers:
ECT2 is named in the same sentence as 75 diseases in open-access papers, as found by Europe PMC text mining. Sharing a sentence is not in itself a finding about the gene and the disease. The quoted sentences say what the papers report.
breast carcinoma (23 papers, 2010 to 2024). "Given that distant metastasis, together with recurrence, are major causes of breast cancer-related deaths, upregulated ECT2 signaling is a potential target to inhibit the generation of metastatic lesions." (PMID 36572949, 2022). "We found that their genome-wide AS programs converge on the ECT2 splice variant including exon 5 (ECT2-Ex5+), whose depletion reduced Doxo resistance, and that correlated with chemotherapy resistance in breast cancer patients." (PMID 31943118, 2020). "Notably, scientists have found that high ECT2 splice variant including exon 5 (ECT2-Ex5+) levels was negatively related to prognosis in breast cancer treated with doxorubicin." (PMID 34326872, 2021). "Consistent with previous report 34, these results suggest that ECT2 is implicated in breast cancer." (PMID 32929379, 2020). "Overall, when combining the different subtypes of breast cancer, high levels of ECT2-Ex5 inclusion (ECT2 Ex5+ / ECT2 Ex5- ratio) were associated with shorter metastasis-free survival in patients that were treated with chemotherapy, but not in patients that were not treated with chemotherapy." (PMID 31943118, 2020). "The results showed that ECT2 deletion associated growth retardation of breast cancer cells could be reverted, to certain extent, by forced expression of MDM2 or USP7/wt, but not USP7/C223S." (PMID 32929379, 2020). "This is the first time, that ECT2 phosphorylation has been directly implicated in breast cancer." (PMID 30278072, 2018). "Regarding breast cancer, analysis of 165 breast cancer specimens and 100 normal samples nominated ECT2 as one of the main causes of the occurrence and development of that cancer; in addition to that, a recent study reported that an increased ECT2 level was highly associated with advanced TNM stage." (PMID 37106813, 2023). "Finally, doxorubicin combination with an oligonucleotide inhibiting ECT2-Ex5 inclusion reduced doxorubicin-resistant tumor growth in mouse xenografts, and high ECT2-Ex5 inclusion levels were associated with bad prognosis in breast cancer treated with chemotherapy." (PMID 31943118, 2020). "RACGAP1 has also been shown to drive breast cancer metastasis by regulating ECT2-dependent mitochondrial quality control." (PMID 38468345, 2024). "Tissue microarrays and multiple public databases were utilized to investigate the relationship between ECT2 level and clinical-pathological features of breast cancer patients." (PMID 36572949, 2022). "Collectively, increased ECT2 level is highly associated with advanced TNM stage, poor differentiation, and loss of hormone receptors of breast cancer." (PMID 36572949, 2022). "ECT2 mRNA data from TCGA showed significantly elevated ECT2 mRNA in breast cancer tissues as well (P < 0.0001)." (PMID 36572949, 2022). "Here, we found increased ECT2 level was highly associated with advanced TNM stage, poor differentiation, and loss of hormone receptors of breast cancer." (PMID 36572949, 2022). "Collectively, we explored the involvement of ECT2 in breast cancer development which would be a potential predictive biomarker and treatment target." (PMID 36572949, 2022). "We also found ECT2 was remarkably higher in breast cancers belonging to Her2 overexpression and Basal-like subtypes." (PMID 36572949, 2022). "Integration analysis using GEO public database and tissue microarray indicates that high ECT2 is an adverse prognostic factor for breast cancer patients." (PMID 36572949, 2022). "Regarding its role in breast cancer progression, RACGAP1 was able to modulate ECT2-dependent mitochondrial quality control to drive breast cancer metastasis." (PMID 36430577, 2022). "Other factors influencing the subcellular location of ECT2 such as Protein kinase Cι-Par6α complex, are meaningful to counteract malignant behaviors of breast cancers." (PMID 36572949, 2022). "IHC scoring results showed that the abundance of ECT2 protein was markedly upregulated in poorly differentiated, ER-, PR- breast cancers." (PMID 36572949, 2022).
breast carcinoma (continued). "Among 152 breast cancer tissues, samples from lymphatic metastasis exhibited higher ECT2 expression relative to primary breast cancer." (PMID 36572949, 2022). "To investigate the biological significance of ECT2 for breast cancer, we performed KEGG and GO enrichment analysis using TCGA and GEO databases." (PMID 36572949, 2022). "Cox regression analysis showed that ECT2 expression is an independent prognostic factor for breast cancer patients." (PMID 36572949, 2022). "To explore the role of ECT2 in breast cancer, we first assessed the ECT2 expression in breast cancers and normal breast tissues." (PMID 36572949, 2022). "In general, elevated ECT2 level was a potential biomarker predicting poor prognosis of breast cancer patients." (PMID 36572949, 2022). "As the guanine nucleotide exchange factor of Rho GTPases, the role of ECT2 (epithelial cell transforming 2) in breast cancer is still unclear." (PMID 36572949, 2022). "Pooled analysis of GEO datasets demonstrated that ECT2 mRNA level was upregulated in breast cancer tissues relative to normal tissues (OR = 2.78, 95%CI = 1.82–4.24)." (PMID 36572949, 2022). "Integration analysis using public databases and tissue microarray indicated that high ECT2 was an adverse prognostic factor for breast cancer patients." (PMID 36572949, 2022). "A recent study on breast cancer revealed that RACGAP1 promotes mitochondrial dynamic driven metastasis through recruiting ECT2 and subsequently activating ERK-DRP1 pathway." (PMID 34239347, 2021). "For example, miR-223-3p repressed the metastasis and progression of osteosarcoma cells by targeting CDH6, over-expression of miR-223-3p suppressed the proliferation, invasion, and migration of breast cancer cells by targeting the ECT2 oncogene." (PMID 33522355, 2021). "Kehan confirmed that RACGAP1 played an essential role in breast cancer metastasis by modulating ECT2-dependent mitochondrial quality control." (PMID 34336648, 2021). "Colony formation assays showed that knockdown of ECT2 severely impeded the colony size and numbers of breast cancer cells including MCF-7 cells, ZR-75-1 cells, and MDA-MB-468 cells." (PMID 32929379, 2020). "In this study, we uncovered a nuclear GEF-independent role of ECT2 in promoting survival of breast cancer cells." (PMID 32929379, 2020). "In a way, our study provides a rationale for validating USP7/ECT2 as a viable therapeutic target for breast cancer." (PMID 32929379, 2020). "This association of high levels of ECT2-Ex5 inclusion with bad prognosis specifically in case of chemotherapeutic treatment, was even more pronounced in the HR+ERBB2– subtype of breast cancer." (PMID 31943118, 2020). "Due to the complex biological heterogeneity of breast cancer, it will be important to determine to what extent the ECT2/USP7 circuit affects breast cancer cell survival across genetically distinct subgroups of breast cancer." (PMID 32929379, 2020). "Altogether, our data identify AS programs controlled by ZRANB2 and SYF2 and converging on ECT2, that participate to breast cancer cell resistance to doxorubicin." (PMID 31943118, 2020). "Meanwhile, we showed the expression level of ECT2 appears to be identical among different molecular subtypes of breast carcinoma, especially for luminal B, Her2-enriched and basal like ones, with datasets from Gene Expression Omnibus (GEO)." (PMID 32929379, 2020). "To understand the role of ECT2 in breast carcinogenesis, we first analyzed the effect of ECT2 depletion on breast cancer cell survival." (PMID 32929379, 2020). "Quantitative analysis of the stainings showed that ECT2 is highly expressed in breast carcinoma and the level of ECT2 expression largely correlates with tumor grade." (PMID 32929379, 2020). "The oncogenic activity of ECT2 works through Rho signaling in breast cancer and hepatocellular carcinoma by transforming inactive GDP-loaded state of Rho to active GTP-loaded state." (PMID 32257108, 2020).
breast carcinoma (continued). "Disease analysis from Oncomine displays that the mRNA expression level of ECT2 is upregulated in breast carcinoma from 12 out of 43 analyses in 4 of 10 datasets 53, and ECT2 is highly expressed in distinct histological breast cancer samples." (PMID 32929379, 2020). "Collectively, these results suggested that ECT2/USP7 circuit is potentially linked to breast carcinogenesis, and ECT2 coordinates with USP7 to promote breast cancer cell survival, at least, via activating oncogenic MDM2." (PMID 32929379, 2020). "Together, for the first time, this implicates ECT2 phosphorylation in breast cancer, which has been proposed as a therapeutic target in lung cancer." (PMID 30278072, 2018). "Further analyses are necessary to determine the potential targeting of ECT2 in breast cancers with low DLC1 expression." (PMID 30278072, 2018). "In the METABRIC dataset of breast tumors from 1,992 patients, high ECT2 expression was correlated significantly with poorer survival including all breast cancer subtypes." (PMID 30278072, 2018). "Recently, PTTG1 was shown to regulate MMP-2 via direct promoter regulation, influence Rho-GEF ECT2, and be involved in the invasion and migration of breast cancer cells by promoting EMT." (PMID 26900962, 2016). "We provide cell line based experimental data for the effect of ECT2 on cell viability; however, further functional validation is still needed to firmly establish the role of the 56 iPAC genes in breast cancer." (PMID 23382830, 2013). "MiR-223 may suppress the development of breast cancer by targeting multiple oncogenic transcripts, including epithelial cell transforming 2 (ECT2), Profilin 2 (PFN2) and NLRP3." (PMID 39125761, 2024). "To assess whether ECT2 expression could predict the prognosis of breast cancer patients, we conducted pooled analysis and found that higher ECT2 mRNA level related to shorter OS (Pooled HR = 1.37, 95%CI 1.19–1.58) and RFS (Pooled HR = 1.17, 95%CI 1.03–1.33)." (PMID 36572949, 2022). "Elevated ECT2 expression was correlated to molecular biomarkers and subtypes of breast cancer." (PMID 36572949, 2022). "Moreover, we explored the relationship between ECT2 abundance and clinic-pathologic features as well as clinical outcomes of patients with breast cancer." (PMID 36572949, 2022). "In this study, by comprehensive analysis of GEO database, TCGA breast cancer dataset, and samples of tissue microarrays, we found that ECT2 expression (at transcriptional and translation levels) was significantly increased in breast cancers compared with non-cancer tissues." (PMID 36572949, 2022). "Our results indicated ECT2 participated in cell proliferation, which might contribute to the malignant biological properties of breast cancer." (PMID 36572949, 2022). "It has been documented inhibiting the activity of ECT2-Rho pathway could effectively inhibit breast cancer metastasis via modifying actin cytoskeleton remodeling." (PMID 36572949, 2022). "Here, we propose that transcriptionally upregulated ECT2 may enhance USP7 self-deubiquitination thus stabilization in breast cancer." (PMID 32929379, 2020). "To investigate that whether, and to what extent, ECT2 is involved in breast carcinogenesis, we first analyze the expression of ECT2 in breast cancer with public datasets." (PMID 32929379, 2020). "Finally, multivariate analysis indicated that high inclusion levels of ECT2-Ex5 were an independent predictive marker of bad prognosis in the subgroup of 120 HR+ERBB2- breast cancer patients treated with chemotherapy." (PMID 31943118, 2020). "Together, these findings point to a tumor-promoting role for ECT2 in breast cancer." (PMID 32929379, 2020). "To confirm the involvement of ECT2 in breast carcinogenesis, we next analyzed, by immunohistochemical (IHC) staining, the expression profiles of ECT2 with samples from different histologic grade breast carcinoma and histologically normal mammary tissues in tumor adjacent regions." (PMID 32929379, 2020).